STAT1 (signal transducer and activator of transcription 1)
Diseases named in the same sentence as STAT1 in open-access papers (continued):
Sharing a sentence is not in itself a finding about the gene and the disease.
neuroblastoma (14 papers, 2013 to 2025). Neuroblastoma (NB) is the most common solid, extracranial childhood tumor. "Additionally, based on a publicly available database, low-risk neuroblastoma patient specimens had statistically significantly more STAT1 expression as compared to high-risk neuroblastoma specimens." (PMID 35159029, 2022). "Discovering significant differences in STAT1 in these neuroblastoma PDXs is an important finding, as this protein is targetable, thereby having the potential to be exploited to further augment tumor responses to oncolytic virotherapy." (PMID 35159029, 2022). "In order to evaluate the potential role of immune checkpoint pathways in the reduction of ADCC over time, the effects of IFNγ treatment on PD-L1 and PD-L2 expression as well as Stat1 activation in neuroblastoma cells was evaluated." (PMID 36525420, 2022). "Based on the current findings, our future investigations will focus on further validation of the role of STAT1 in conferring resistance to oHSV in neuroblastoma, and the utility of combining oHSV with small molecular inhibitors of STAT signaling." (PMID 35159029, 2022). "Our results suggest that IFNγ induces the expression of PD-L1 via activation of Stat1 in neuroblastoma." (PMID 36525420, 2022). "In order to confirm that IFNγ induced PD-L1 via Stat1, we treated six neuroblastoma cell lines with IFNγ at two doses (1 and 10 ng/ml) for 24 hours." (PMID 36525420, 2022). "Using the SH-SY5Y neuroblastoma cell line and HIV-infected humanized mice, we examined the effects of the cART drugs, HIV Tat protein, and HIV-1 virus on STAT1 and IFIT3 expression." (PMID 40936921, 2025). "On the other hand, CAFs derived from neuroblastomas have shown that IL-6 activates various signaling pathways, including STAT3, ERK1/2, and STAT1, in tumor cells." (PMID 38606999, 2024). "Moreover, PPAPs were recently described as selective agents in highly resistant neuroblastoma entities, exerting a pleiotropic effect that involves the downregulation of transcription factors which may interact with viral promoters like Myc, Myb and Stat1/3." (PMID 26260344, 2015). "Therefore, STAT1 and p38 did not appear to be potential mechanisms of cellular resistance to oHSV in these neuroblastoma cell lines." (PMID 24130898, 2013).
osteoporosis (14 papers, 2010 to 2025). A condition of reduced bone mass, with decreased cortical thickness and a decrease in the number and size of the trabeculae of cancellous bone (but normal chemical composition), resulting in increased fracture incidence. "Previous studies have identified that STAT1, as an important factor involved in osteoporosis, is importance for bone metabolism." (PMID 36918560, 2023). "We next found fludarabine treated BMMSCs significantly stimulated osteoporosis but reduced adipogenesis, suggesting STAT1 signaling pathway have an impact on BMMSCs differentiation." (PMID 37748319, 2023). "The STAT1 signaling pathway is strongly activated in the pathogenesis and progression of osteoporosis." (PMID 32963569, 2020). "IFN-β is a principal mediator in the pathogenesis of osteoporosis by inhibiting osteoclasts and inducing and activating STAT1." (PMID 25563300, 2015). "Additionally, the results demonstrated that AL improves bone loss in osteoporosis through the upregulation of the interferon‐β/signal transducer and activator of transcription 1 pathway (IFN-β/STAT1), which is strongly related to the osteoporosis pathogenesis." (PMID 40523987, 2025). "To identify mechanisms of SPTBN1 in osteoporosis, we explored pathways related to SPTBN1 by STRING website and found that SPTBN1 may associate with TGF-β/Smad3 and STAT1/Cxcl9 signaling pathways." (PMID 33816505, 2021). "Thus we conclude that the STAT1 gene is important in human circulating monocytes in the etiology of osteoporosis." (PMID 19594299, 2010). "Thus, SPTBN1 may regulate osteoblast by TGF-β/Smad3 and STAT1/Cxcl9 signaling pathways in osteoporosis." (PMID 33816505, 2021). "Besides, these results suggested that the effect of SPTBN1 in osteoporosis also might be mediated by the STAT1/Cxcl9 signaling pathway." (PMID 33816505, 2021). "The results showed that overexpression of SPTBN1 significantly suppresses the development of primary osteoporosis by modulating VEGF, TGF-β/Smad3, and STAT1/Cxcl9 signaling pathways." (PMID 33816505, 2021). "Taken together, these results suggested that SPTBN1 suppressed primary osteoporosis by facilitating the proliferation, differentiation, and inhibition of apoptosis in osteoblasts via the TGF-β/Smad3 and STAT1/Cxcl9 pathways." (PMID 33816505, 2021). "In both bone cell types, the transcription factor STAT1 is activated by IFN-β and seems to participate significantly in the pathogenesis of osteoporosis." (PMID 25563300, 2015). "Therefore, SPTBN1 may suppress primary osteoporosis of osteoblasts through Smad3/TGF-β and STAT1/Cxcl-9 signaling pathways." (PMID 33816505, 2021). "In summary, our results support the fact that the STAT1 gene in circulating monocytes plays important roles in bone metabolism and also suggests that gene expression of the STAT1-mediated IFN pathway may be important for osteoporosis." (PMID 19594299, 2010).
renal fibrosis (14 papers, 2017 to 2024). A final common manifestation of a wide variety of chronic kidney diseases characterized by glomerulosclerosis and tubulointerstitial fibrosis. "The purpose of this study was to investigate the potential effect of anti-dsDNA IgG on the regulation of SOCS1 signals and also the molecular mechanism underlying SOCS1-KIR and JAK2/STAT1 interaction in the pathogenesis of renal fibrosis." (PMID 28620377, 2017). "It was found that miR-27b-3p overexpression alleviated renal fibrosis in TGF-β1-induced HK-2 cells through STAT1 inactivation." (PMID 36714464, 2023). "It is noteworthy that STAT1 has been shown to be protective against renal fibrosis during renal injury." (PMID 36602864, 2023). "In the inactivated state, STAT1 can reverse podocyte injury triggered by high glucose and it plays a key role in renal fibrosis and apoptosis." (PMID 34164430, 2021). "SOCS1 participates in renal fibrosis by downregulating JAK2/STAT1-mediated cytokine signaling in LN." (PMID 30214448, 2018). "Therefore, overexpression of miR-27b-3p diminished the expression of p-STAT1 and STAT1, promoting renal fibrosis induced by TGF-β1." (PMID 38474021, 2024). "Moreover, overexpression of miR-27b-3p in UUO inhibited renal fibrosis via downregulation of signal transducers and activators of transcription 1 (STAT1) expression." (PMID 37440209, 2023). "Thus, the SOCS1/p-JAK1/p-STAT1 pathway contributes to renal fibrosis in folic acid-induced RIF mice." (PMID 35990680, 2022). "In conclusion, miR-27b-3p overexpression could alleviate renal fibrosis via suppressing STAT1 in vivo and in vitro." (PMID 33454903, 2021). "In this study, the results indicated that aberrant expression of miR-27b-3p plays an important role in the progression of renal fibrosis, and overexpression of miR-27b-3p could attenuate the progression of renal fibrosis through inhibition of STAT1 signaling." (PMID 33454903, 2021). "All these results illustrated that overexpression of miR-27b-3p could alleviate renal fibrosis in vivo via suppressing STAT1." (PMID 33454903, 2021). "Furthermore, overexpression of miR-27b-3p attenuated UUO-induced renal fibrosis via downregulation of STAT1, α-SMA and collagen III." (PMID 33454903, 2021). "Recent evidence suggested that STAT1 activation prevented renal fibrosis by regulating macrophages differentiation and renal infiltration upon chronic kidney injury, indicating a protective role of STAT1 in renal fibrosis." (PMID 32708044, 2020). "In this study, we found that miR-27b-3p could alleviate renal fibrosis via targeting STAT1." (PMID 33454903, 2021). "Suppressor of cytokine signaling 1 (SOCS1) participates in renal fibrosis by downregulating Janus kinase 2 (JAK2)/signal transducer and activator of transcription 1 (STAT1)-mediated cytokine signaling." (PMID 28620377, 2017). "Although rhein has been widely demonstrated to protect against renal fibrosis, only two previous studies have reported that rhein protected against renal fibrosis by inhibiting the NF-ƙB p65 protein expression and lincRNA-COX2/miR-150-5p/STAT1 axis." (PMID 35002735, 2021). "In conclusion, anti-dsDNA IgG downregulates SOCS1 expression, activates JAK2/STAT1 signals, and contributes to renal fibrosis; its peptide blockade may restore the SOCS1 inhibitory effect on the production of profibrotic cytokine, and finally ameliorate renal fibrosis in LN." (PMID 28620377, 2017). "Studies have shown that 1,25(OH)2D3 beneficially affects renal fibrosis in DN via TGF-β1, signal transducer and activator of transcription 1, protein tyrosine phosphatase nonreceptor type 2, and Nrf2." (PMID 31781203, 2019).
sarcoidosis (14 papers, 2013 to 2026). Sarcoidosis is a multisystemic disorder of unknown cause characterized by the formation of immune granulomas in involved organs. "STAT1 transcripts were also upregulated across cell types, and this has been shown to have increased expression in granulomas during sarcoidosis." (PMID 41586350, 2025). "In sarcoidosis, STAT1 is primarily activated in granuloma macrophages while activated STAT3 is in T-cells and B-cells thus indicating a role for the JAK-STAT pathway in the pathogenesis of sarcoidosis." (PMID 39345281, 2024). "However, the most striking feature of sarcoidosis lesional T cells was their very strong and significant upregulation of STAT1 and IFNG." (PMID 39989459, 2025). "The discrepancy in STAT1 expression may account for the difference between Langhans-type giant cells formed in sarcoidosis and foreign-body giant cells." (PMID 38038136, 2023). "Biomarkers including TTN (titin) and STAT1 are widely involved in sarcoidosis." (PMID 38137330, 2023). "Genes regulated by STAT1 in particular showed to be elevated in the blood of sarcoidosis patients." (PMID 32760396, 2020). "A heatmap analysis further demonstrated an upregulation of key genes involved in these pathways, particularly in the progressive sarcoidosis group, including CSF2RB, CSF2RA, IL3RA, STAT5A, and STAT1." (PMID 41476976, 2025). "PSMB9, a gene downstream of STAT1, which is known to integrate with IFNG and to play a proteolytic role in MHC1 antigen presentation, has been reported to be upregulated in sarcoidosis." (PMID 36203777, 2022). "For example, here, among other genes, STAT1, IL10RA, and PTEN were underexpressed in sarcoidosis CD14 monocytes compared to controls while CXCR4, ATG12, HIF1A, CCR1, and IER3 were overexpressed, consistent with the effects of TGFB1 signaling." (PMID 33363531, 2020). "Reanalysis of a sarcoidosis scRNA-seq dataset revealed that, similar to NL and NXG, sarcoidosis lesional fibroblasts expressed high levels of MHC (e.g., HLA-B and HLA-DRA), CD74, PLOD2, STAT1, TNC, PRSS23, PSMB9, and CXCL9." (PMID 39989459, 2025). "Analysis of tissue and circulating mononuclear cells from patients with sarcoidosis consistently revealed a constitutive JAK-STAT activation and immunohistochemistry showed constitutive activation of STAT1 in granuloma macrophages and STAT3 in surrounding lymphocytes." (PMID 39431514, 2024). "In contrast to the APECED serum (containing high concentrations of IFNα neutralizing autoantibodies), we could not detect an inhibitory effect of serum from TB (n = 6) or sarcoidosis (n = 6) with high anti-IFNα2 reactivity on IFNα induced STAT1 phosphorylation in THP-1 cells." (PMID 39309852, 2024).
Stroke (14 papers, 2008 to 2024). Sudden impairment of blood flow to a part of the brain due to occlusion or rupture of an artery to the brain. "Microglial polarization is triggered by DAMPs and IFNγ stimulation, which activate the NF-kB and STAT1 pathways, similar to macrophages, resulting in the release of cytokines including IL-1β and TNF-α that cause neuronal death following stroke." (PMID 39062789, 2024). "Third, our study established a direct role for Mi/MΦ STAT1 in determining long-term stroke outcomes." (PMID 37516843, 2023). "By selectively deleting STAT1 in Mi/MΦ, the post-stroke neuroinflammation can be effectively mitigated, leading to improved long-term functional recovery." (PMID 37516843, 2023). "In compliance with the in vitro data, prophylactic atRA treatment inhibited STAT1 signaling in neutrophil at 1–3 days after stroke in vivo." (PMID 31472680, 2019). "Post-stroke angiogenesis resembles in many ways the angiogenesis in tumors, i.e., the newly formed vessels are leaky via the Il6r/Il6st/STAT1/3 pathway." (PMID 24672479, 2014). "While the inductionof Stat1 and Stat3 promotes postischemic inflammation, and Stat-1 knockout micedevelop less severe stroke lesions in the CNS, activation of PPARs preventspostischemic inflammation and neuronal damage." (PMID 18670616, 2008). "Next, we examined whether alteration of Mi/MΦ phenotype by STAT1 deletion led to secondary changes in the brain inflammation profiles at the subacute stage after stroke." (PMID 37516843, 2023). "Importantly, in vivo selective deletion of STAT1 drives Mi/MΦ toward an inflammation-resolving phenotype, resulting in mitigation of neuroinflammation and improvement of long-term stroke outcomes." (PMID 37516843, 2023). "However, given the long-lasting functional improvement elicited by STAT1 mKO after MCAO, we sought to determine if STAT1 mKO affected the long-term integrity of the post-stroke brain." (PMID 37516843, 2023). "Together, these data suggest that STAT1 is elevated and activated in post-stroke Mi/MΦ at the subacute stage (24 and 72 h) and may influence the function of these cells." (PMID 37516843, 2023). "It remains unknown whether STAT1 regulates Mi/MΦ function and affects the evolving long-term neurological recovery—the primary endpoint of clinical stroke." (PMID 37516843, 2023). "In conclusion, our study demonstrated that EE pretreatment could protect the brain after stroke by inhibiting the p38 MAPK/STAT1 pathway." (PMID 36572761, 2023). "To this end, we tested whether STAT1 mKO had similar beneficial effect in improving long-term outcome after stroke in female mice." (PMID 37516843, 2023). "Furthermore, Upstream Regulator analysis predicted several members of the STAT family to be activated in post-stroke microglia, with STAT1 being the most activated (z-score = 5.85, p = 9.84 × 10–19)." (PMID 37516843, 2023). "We found that the deletion of STAT1 in Mi/MΦ resulted in less brain inflammation at the subacute stage after ischemic stroke, manifested by less infiltration of blood-borne immune cells and reduced content of cytokines in the post-stroke brain." (PMID 37516843, 2023). "Stat1 and Stat2 are new players in the stroke search for novel therapeutic targets." (PMID 24672479, 2014). "An increased expression of the newly identified stroke genes Il6ra, Il6st, S100a4, Stat1, and Stat2, but also the known genes Col1a1, Col1a2, Col3a1, has been implicated in blood vessel remodeling and contributes to vascular rarefaction, leakage, and intracranial aneurysms." (PMID 24672479, 2014). "The transcription factor signal transducer and activator of transduction 1 (STAT1) has been found to contribute to acute neuronal death (in the first 24 h) following ischemic stroke, but its effects on Mi/MΦ and influence on long-term stroke outcomes have yet to be determined." (PMID 37516843, 2023).
Stroke (continued). "Several transcription factors, such as STAT1, NF-κB p65, and IRF5, were demonstrated to be involved in proinflammatory microglial polarization after stroke." (PMID 37908012, 2023). "Recent studies have shown that STAT1 antagonistic regulator STAT6 knockout prompted M/M toward a proinflammatory phenotype, along with impaired clearance of dead/dying neurons and increased cerebral inflammation and neuronal death in stroke mice." (PMID 39107960, 2024). "Collectively, these data suggest that targeted deletion of STAT1 only in Mi/MΦ does not affect neuronal death or stroke outcome at the acute injury stage (24 h after MCAO)." (PMID 37516843, 2023). "To confirm the activation of STAT1 in Mi/MΦ after stroke, we conducted RNA-seq analyses on microglia enriched from the post-stroke brain 3 days after MCAO and from non-injury sham controls using FACS." (PMID 37516843, 2023). "The proportion of CD45high cells (macrophages) in STAT1-immunopositive cells gradually increased from 2 to 72 h after MCAO, likely reflecting the infiltration of blood monocytes/macrophages into the post-stroke brain." (PMID 37516843, 2023). "In a study using a different model of stroke (tMCAO for 30 min), PrP0/0 mice had an increased activation of ERK1/2, signal transducer and activator of transcription 1(STAT-1), JNK1/2, and caspase-3 at 3 h after reperfusion, which was neither observed in WT nor in tga20 mice." (PMID 32630841, 2020). "Furthermore, there have been no studies conducted to assess the impact of STAT1 knockout on long-term stroke outcomes." (PMID 37516843, 2023). "Mi/MΦ-targeted STAT1 KO does not provide immediate neuroprotection but augments inflammation-resolving actions of Mi/MΦ, thereby facilitating long-term functional recovery after stroke." (PMID 37516843, 2023). "STAT1 and STAT2 are reported to be involved in signaling responses to interferon; their reduction in multiple EA treatment might contribute to anti-inflammation against the secondary injury after stroke." (PMID 25126102, 2014).
triple-negative breast carcinoma (14 papers, 2017 to 2025). An invasive breast carcinoma which is negative for expression of estrogen receptor (ER), progesterone receptor (PR), and human epidermal growth factor receptor 2 (HER2). "In conclusion, ATM knockdown upregulates HLA expression in triple-negative breast cancer through activation of the c-Jun/TNF-α/p-STAT1 signaling pathway." (PMID 40825766, 2025). "M2 macrophages also promote triple-negative breast cancer progression through the JAK1/STAT1 pathway." (PMID 35269804, 2022). "Previously, we have demonstrated that high expression of signal transducer and activator of transcription 1 (STAT1) and CD74 is associated with triple-negative breast cancer." (PMID 29190904, 2017). "STAT1-dependent IDO overexpression blocked the activation of T cells, which was related to an increase in PD-L1 expression in high-level triple-negative breast cancer (TNBC) cells." (PMID 34838003, 2021).